USP10 (ubiquitin specific peptidase 10)
Diseases named in the same sentence as USP10 in open-access papers (continued):
Sharing a sentence is not in itself a finding about the gene and the disease.
cancer (continued). "Several members of the DUB family are known to contribute to carcinogenesis, including USP1, USP2, USP7 and USP22, while other DUBs are down-regulated in human cancers, including USP10 and BAP1." (PMID 27030989, 2016). "Here the authors identify TOP2a as substrate for RNF168 and USP10; providing a link between the RNF168/USP10 axis, TOP2a and the response to anti-cancer drugs that target TOP2." (PMID 27558965, 2016). "In addition, this review discusses the potential applications of USP10 inhibitors as targeted drugs for cancer therapy." (PMID 41892309, 2026). "An analysis of large-scale, genome-wide CRISPR-Cas9 KO data sets indicated that USP10 is classified as an essential gene for the survival of the majority of cancer cells as determined by both CRISPR-engineered regulatory element scoring (CERES) and CHRONOS analysis." (PMID 40991650, 2025). "USP10 imprints the cellular identity of cancer cells, as loss of USP10 altered the transcriptional profiles towards a non-transformed, differentiated state." (PMID 39443725, 2024). "USP10 plays an important role in many biological processes and cancers." (PMID 39517125, 2024). "Considering that USP13 and USP10 also have the role of regulating substrate deubiquitination and inhibiting the degradation of substrate ubiquitin proteasome, and are also widely involved in life processes such as cancer and cell apoptosis." (PMID 39517125, 2024). "These investigations have demonstrated that USP10 has a key contribution to malignant tumors." (PMID 37184153, 2023). "These phenomena suggest that the role of USP10 in cancer is rather unclear and may depend on the context and environmental settings such as hypoxia." (PMID 37371055, 2023). "Besides, USP10 has been shown to be involved in cancer cell migration by regulating the stability of the EMT-transcription factor Slug/SNAI2 and Vimentin." (PMID 37919637, 2023). "There is now evidence to support that USP10 plays diverse roles in different types of cancer." (PMID 37786443, 2023). "USP10 plays multiple roles in many diseases including human cancers." (PMID 35627217, 2022). "Notably, in 14 cancers, the expression of USP10 correlated significantly with B cell infiltration levels." (PMID 35433424, 2022). "Furthermore, it would be necessary to identify suitable patients for USP10 inhibitor treatment based on their cancer type." (PMID 36248971, 2022). "USP10 has lower expression in GC than in para-cancer tissues." (PMID 35627217, 2022). "Moreover, the expression of USP10 correlated strongly with the infiltration level of dendritic cells in 10 cancers, with neutrophils in 24 cancers, with macrophages in 18 cancers, with CD4+ T cells in 13 cancers, and with CD8+ T cells in 15 cancers." (PMID 35433424, 2022). "Therefore, the relationship between USP10 expression and immune cell infiltration in 39 types of cancer was assessed using the TIMER database." (PMID 35433424, 2022). "In 2020, Bhattacharya summarized the partial roles of USP10 in different cancers." (PMID 35627217, 2022). "It would be intriguing to explore whether a synergistic therapy combining USP10 and an effector of DNA damage would be a more efficient strategy for cancer treatment." (PMID 35627217, 2022). "USP10 also participates in the development of cancer in a context-dependent manner." (PMID 34967276, 2022). "It is encouraging us to explore whether tazemetostat or other EZH2 inhibitors cure cancers in an USP10-independent manner." (PMID 35627217, 2022). "USP10 is a highly conserved deubiquitinating enzyme among over 50 members and is extensively involved in the initiation and progression of a broad spectrum of cancer types, DNA damage response, and signaling pathways." (PMID 35987808, 2022). "In addition to the differential effects of USP10 in different cancers, USP10 can be a double-edged sword in the same cancer." (PMID 35627217, 2022).
cancer (continued). "Furthermore, the role of USP10 in cancer has recently been expanded to include deubiquitinase activity for PTEN." (PMID 36385557, 2022). "Emerging evidence has demonstrated that USP10 is a double-edged sword in human cancers." (PMID 35627217, 2022). "Taken together, the development of specific and efficient USP10 inhibitors based on USP10’s oncogenic role and for different cancer types could be a promising therapeutic strategy." (PMID 35627217, 2022). "Altogether, our results suggest that USP10 may be required for modulating the increased demand for protein folding ability, especially in cancer cells, and prevent potentiation of ER stress." (PMID 36543867, 2022). "USP10’s role in cancer has been intensively studied in the past decade." (PMID 34746935, 2021). "Here, we will discuss USP10’s functions in cancer by examining its various known substrates." (PMID 34746935, 2021). "Below we elaborate the context-dependent roles of USP10 in cancer." (PMID 33277473, 2020). "Together, these reports indicate that USP10 inhibition has significant potential in cancer therapy." (PMID 33277473, 2020). "Nevertheless, the roles of USP10 in cancer metastasis remain to be clarified." (PMID 31721429, 2020). "However, we noticed that all SGs nucleators (TIA-1, TIAR, G3BP1, G3BP2, and CAPRIN-1) have an “enhancing” effect on cancer development properties, whereas USP10, a SGs inhibitor, has anti-cancer properties." (PMID 32882814, 2020). "USP10 is well documented involving in the progression and development of several cancers." (PMID 33197885, 2020). "All of these studies showed that USP10 can function as an oncogene or tumor suppressor, so intervention in USP10 may be a candidate anti-cancer strategy." (PMID 30319415, 2018). "Furthermore, we describe a therapeutically actionable target, USP10, inhibitors to which may be used in the near term to circumvent PI3K resistance in cancer types harboring PIK3CA mutations." (PMID 40991650, 2025). "It is reported that USP10 could affect cancer progression in different ways." (PMID 40517136, 2025). "However, the role of USP10 in cancer regulation is controversial." (PMID 38689092, 2024). "Interestingly, USP10 was reported to have opposing roles in the same cancer." (PMID 37371055, 2023). "Therefore, it is necessary to further clarify the role of quercetin and explore whether the inhibition of USP10 is the major mechanism for cancer treatment." (PMID 35627217, 2022). "Therefore, targeting USP10 in cancer is highly context-dependent." (PMID 34746935, 2021). "Thus, USP10 is involved in diverse cellular functions, and its involvement in multiple human pathologies is not surprising; USP10-associated pathologies include cancer and neurodegenerative diseases." (PMID 33277473, 2020). "From other cancers it is also reported that besides USP28, the deubiquitinases USP7, USP8, USP10 and USP11 interact with NICD and regulate NOTCH1 signaling." (PMID 40456839, 2025).
cancer (continued). "Increasing evidence has suggested that ubiquitin-specific protease 10 (USP10), a deubiquitinating enzyme, plays an essential role in targeted protein degradation and participates in cancer progression." (PMID 39430239, 2024). "Several DUBs, including USP10, USP18, USP22, USP43, and USP51 have been identified as key regulators of ZEB1 stability, thereby promoting proliferation, migration and invasion of cancer cells across different malignancies." (PMID 39736693, 2024). "The deubiquitination of SIRT6 by USP10 and USP48 inhibits cancer formation by preventing the growth and development of cancer cells." (PMID 37175631, 2023). "Previous studies demonstrated that USP10 could deubiquitinate and stabilize Yes-associated protein (YAP)/PDZ-binding motif (TAZ), HDAC6, FMS-like tyrosine kinase 3 (FLT3), spleen tyrosine kinase (SYK) and topoisomerase Iiα (TOP2α), thus promoting cancer progression." (PMID 36163081, 2022). "In these malignancies, USP10 was shown to inhibit c-Myc transcription, and AKT/mTOR activation to inhibit cancer cell growth." (PMID 36543867, 2022). "Since USP10 is frequently downregulated in human cancers, including lung, gastric, colorectal, and small intestinal carcinomas, restoration of USP10 function may represent a new therapeutic strategy for cancer prevention and treatment through PTEN reactivation." (PMID 36385557, 2022). "HAUSP/USP7, USP10, USP11, USP13, OTUD3, and Ataxin-3 have all been recently identified as PTEN DUBs that control PTEN activity in different cancer-specific contexts." (PMID 36385557, 2022). "Ubiquitin-specific peptidase 10 (USP10) is a highly conserved deubiquitinating enzyme, and is extensively involved in the progression of a broad spectrum of cancers." (PMID 36163081, 2022). "Thus, USP10 might exert a fundamental function in the TME of cancers." (PMID 35433424, 2022). "Here, we review the role of USP10 in tumors and regulation of immune responses and provide new insights into the USP family as potential targets for cancer therapy." (PMID 36248971, 2022). "Although USP10 functionally acts as a tumor suppressor in different types of cancer, it also exerts a proto-oncogenic activity in AML by regulating cancer stem cells properties." (PMID 32674429, 2020). "The results showed that both USP10 and HDAC6 expression were significantly (p < 0.01) increased in cancer patient samples compared to normal tissues." (PMID 32382008, 2020). "Recently, of the proteins in the ubiquitin-specific protease (USP) family, USP10 was found to induce EMT and aggressiveness in human cancer." (PMID 31234902, 2019). "To answer the question whether POLR2A participates in the USP10‐medidated transcriptional activation of SLC7A11 and inhibition of cancer ferroptosis, we knocked down the expression of POLR2A in USP10‐overexpressed Cal27 cells." (PMID 40605431, 2025). "Although these authors investigated the role of USP10-dependent regulation of FOXQ1 in the context of acute kidney injury, these findings may have implications for cancer biology as well." (PMID 39777582, 2025). "Furthermore, since CMA has been implicated in the degradation of various disease-associated proteins beyond neurodegenerative diseases, targeting USP10-regulated CMA represents a promising therapeutic strategy for treating these conditions, including cancer." (PMID 40419127, 2025).
cancer (continued). "For example, since 2015, several DUBs-targeted agents, including VLX1570 (targeting USP14), P22077 (targeting USP7/USP10/USP47), P5091 (targeting USP7/USP47), and spautin-1 (targeting USP10/USP13), have been investigated in the clinic to treat certain types of cancers." (PMID 39522000, 2024). "In addition, we showed that USP10 knockdown decreased the levels of YAP1, which is an important positive regulator of migration and invasion in many cancers." (PMID 37184153, 2023). "DUBs are critical key players in diverse processes such as (i) spermatogenesis (e.g. USP2, USP8, USP9y, USP14, USP26, Uchl-1, Uchl-3 and CYLD), (ii) cancer biology (e.g. USP7, USP10 and USP11), and (iii) stemness and differentiation (e.g. USP7, USP9x, USP22, USP44 and Psmd14)." (PMID 28659380, 2017). "We further fused Caprin1 and USP10-derived peptides with a cell-penetrating peptide; the synthesized TAT-SIP-C1/2 and SIP-U1-Antp could effectively block sorafenib-induced SGs and improve the sensitivity of cancer cells to sorafenib-induced cell death." (PMID 38731625, 2024). "Given the significance of USP10, USP11, USP13 and OTUD3 in PTEN stability, the development of a potent PTEN activation approach through manipulation of these DUBs may represent an attractive strategy for cancer prevention and treatment." (PMID 36385557, 2022). "No USP10 inhibitors have been considered in clinical trials for cancer treatment." (PMID 36248971, 2022). "Additionally, we found that USP10 acts as an oncogene in some cancers but not in others, due to the different functions of genes deubiquitinated by USP10." (PMID 36248971, 2022). "Spautin-1, a small-molecule inhibitor, has been shown to inhibit the deubiquitinase activities of both USP10 and USP13, leading to increased ubiquitination and degradation of Beclin1 in the Vps34 complex, and an eventual decrease in the level of autophagy in cancer cell lines." (PMID 36248971, 2022). "Other cancer progression-related genes that became differently expressed in PNX0010 cells under PARG overexpression are serpin family E member 1 (SERPINE1), colony-stimulating factor 2 (CSF2 or GM-CSF), ubiquitin specific peptidase 10 (USP10), and growth differentiation factor 15 (GDF15)." (PMID 34638458, 2021). "However, a recent study revealed that P22077 and HBX19818 may also inhibit the deubiquitinase activity of USP10 and induce the proliferation inhibition of mutant-FLT3 (FLT3-ITD)-positive cancer cells." (PMID 30319415, 2018).
infection (10 papers, 2020 to 2025). The state of being infected such as from the introduction of a foreign agent such as serum, vaccine, antigenic substance or organism. "In the proteomic data obtained from the TMT-labeled experiment, we found a decreased expression level of LC3b protein 60 min post-infection (PRIDE DOI: 10.6019/PXD043492) together with decreased activity of the USP10 enzyme." (PMID 37841261, 2023). "We show increased total activity of deubiquitinating enzymes (DUBs) in human macrophages after infection, while confirm reduced enzymatic activities of two specific DUBs (USP10 and UCH-L5), and demonstrate increased activity of USP25." (PMID 37841261, 2023). "As another stress granule-inhibiting protein, USP10 could potentiate the effects of nsP3 in dismantling the stress granules, but the specific downstream effects of USP10 in the context of infection remain to be characterized." (PMID 40193402, 2025). "Interestingly, the SL-I of ZIKV can interact with proteins related to stress granules, such as Caprin-1, G3BP1, G3BP2 and USP10, to assess the success of infection." (PMID 36982407, 2023). "Next, we established USP10 overexpression or knockdown NSCLC cell lines with lentiviral infection." (PMID 35277183, 2022). "We revealed that USP10, UCH-L5, and USP25 exhibited higher concentrations in exosomes after infection compared to uninfected control." (PMID 37841261, 2023). "USP10 and UCH-L5 showed then a decreased activity while USP25 showed an increased activity at 60 min after infection, which was confirmed by a Western blot analysis." (PMID 37841261, 2023). "Using label-free proteomics of specifically entrapped active DUBs, we identified decreased amounts of active USP10 and UCH-L5 in macrophages 60 min post-infection." (PMID 37841261, 2023). "Using this proteomic approach, as well as Western blot immunoassays, we showed unchanged expression on the protein level for USP10, UCH-L5, and USP25 in THP-1 cell lysates after infection." (PMID 37841261, 2023). "We next identified greater amounts of UCH-L5, USP10, and USP25 in THP-1 derived exosomes after F. tularensis FSC200 infection." (PMID 37841261, 2023). "Using proteomic analysis of selectively isolated enzymatically active DUBs, we confirmed decreased amounts of active USP10 and UCH-L5, as well as increased amount of active USP25, in cells after infection." (PMID 37841261, 2023). "Regarding DUB expression, no apparent differences were found throughout infection in the levels of HAUSP, also called USP7, UCHL1, A20, USP10, STAMBP, and CYLD." (PMID 36851696, 2023).
neurodegenerative disease (4 papers, 2019 to 2025). A disorder of the central nervous system characterized by gradual and progressive loss of neural tissue and neurologic function. "Collectively, these findings suggest that USP10 is a critical factor to control protein aggregation, aggresome formation, and cytotoxicity in neurodegenerative diseases." (PMID 33277473, 2020).
bacterial infections (1 paper, 2023). "We specifically focused on three enzymes reported to be involved in the immune response to bacterial infections: USP10, UCH-L5, and USP25." (PMID 37841261, 2023).
hematological malignancies (1 paper, 2021). "In recent years, some DUBs, such as USP7, USP9X and USP10, have been identified as promising therapeutic targets in hematological malignancies." (PMID 34454635, 2021).
infectious disease (1 paper, 2020). A disorder directly resulting from the presence and activity of a microbial, viral, or parasitic agent in humans. "USP10 plays an important role in neurodegenerative and infectious diseases." (PMID 33277473, 2020).
neurological disorders (1 paper, 2025). "USP10 has been shown to regulate neurological diseases by mediating pathways such as immune response, oxidative stress, and apoptosis." (PMID 41284210, 2025). "Additionally, we summarize recent progress in the development and application of USP10 modulators and potential therapeutic strategies targeting USP10 in neurological disorders." (PMID 41284210, 2025).
USP10 also shares sentences with these, for which no sentence is quoted: diabetes mellitus (3 papers); nasopharyngeal carcinoma (3); lymphoma (2); pancreatic adenocarcinoma (2); triple-negative breast carcinoma (2); ZIKV infection (2); -Deficient (1); adult T-cell leukemia (1); asthma (1); brain cancer (1); Breast Tumor (1); cerebral infarction (1); cerebrum cancer (1); cholangiocarcinoma (1); CNS cancer (1); dysplasia (1); fibrosarcoma (1); frontotemporal dementia (1); head and neck cancer (1); heart failure (1); hypertrophy (1); immune system diseases (1); kidney cancer (1); large cell lung carcinoma (1); lung fibrosis (1); myocardial ischemia (1); neuroblastoma (1); nonalcoholic steatohepatitis (1); Parkinson’s (1); sarcoma (1).